SOCS3 (suppressor of cytokine signaling 3)
Diseases named in the same sentence as SOCS3 in open-access papers (continued):
Sharing a sentence is not in itself a finding about the gene and the disease.
tumor (continued). "Knockdown of SOCS3 in JAK2 V617F expressing Ba/F3 cells further enhances phosphorylation of STAT3, STAT5 and extracellular signal-regulated kinase 1/2 (ERK1/2) suggesting a tumour suppressor role for SOCS3 in the mutant state." (PMID 34193229, 2021). "Recently, it has been reported that the lncRNA GAS5, a reported tumor suppressor, functions as a ceRNA for miR-221, and thus regulates the expression of the suppressor of cytokine signaling 3 (SOCS3) protein." (PMID 34203589, 2021). "Less is known about the roles of SOCS4 than about the roles of SOCS2 and SOCS3 in tumor growth and malignancy." (PMID 34120621, 2021). "The uptake of KIRESS, in 4T1 tumor-bearing BALB/c mice, was more efficient in primary tumor as well as in the bone marrow and spleen compared to non–tumor-bearing mice, allowing an easy access for SOCS3 mimetic to disseminated tumor cells in these organs." (PMID 35047557, 2021). "On the other hand, inhibition from JAK-STAT3 signaling with SOCS family including SOCS3 induced activation of antitumor immunity in the tumor microenvironment." (PMID 33659045, 2021). "In the HCC tissues, PD-L1 was mainly expressed in the cellular membrane and cytoplasm of tumor cells in a diffuse manner; CD4/CD8, CD276 and SOCS3 protein were also mainly found in the cytoplasm and membrane of tumor cells." (PMID 32742491, 2020). "Suppressor of cytokine signaling 3 (SOCS3) methylation in both HCC tissue and plasma was also found to be associated with tumor size and differentiation, metastasis, and recurrence, as well as with poorer prognosis." (PMID 32443747, 2020). "Taken together, these data indicate an indispensable tumor‐suppressor role for the hsa_circ_0007874/miR‐760/SOCS3 pathway in OVA." (PMID 32023009, 2020). "CircTADA2A-E6 displays tumor-suppressor properties and functions as a miR-203a-3p sponge and restores the expression of its target SOCS3." (PMID 33195421, 2020). "CUEDC2 regulates the phosphorylation of STAT3 by regulating the stabilization of the SOCS1 or SOCS3 protein in tumor cells." (PMID 32393737, 2020). "In summary, the data suggest that hsa_circ_0007874 acts as a tumor suppressor by regulating the miR‐760/SOCS3 axis, highlighting its potential as an effective therapeutic target for OVA." (PMID 32023009, 2020). "The results showed that SOCS3 promoter was hypermethylated in one third of the patients, which was closely related to tumor size, tumor differentiation degree and TNM stage." (PMID 32751889, 2020). "We first found a significant correlation between the expression of PD-L1 and SOCS3 in HCC tumor tissue." (PMID 32742491, 2020). "SOCS1 expression was comparable between tumor tissues and adjacent normal tissues in the TCGA-LIHC dataset, whereas SOCS3 expression was significantly reduced in tumor tissues." (PMID 32807134, 2020). "Univariate analysis revealed that Edmondson grading (P=0.005), tumor number (P=0.004), pT categories (P=0.032), PD-L1 expression (P=0.004) and SOCS3 expression (P=0.019) were independent indicators for overall survival." (PMID 32742491, 2020). "As an important tumor suppressor gene, the abnormal expression or function of SOCS3 plays an important role in the occurrence and progression of various tumors, including OVA." (PMID 32023009, 2020). "They showed that SOCS3 expression is downregulated in HCC patients, as well as in cells transfected with miR-221, and that in vitro miR-221 inhibition or SOCS3 overexpression inhibits tumor growth." (PMID 32717951, 2020). "Together, SOCS-1 and SOCS-3 play important roles as tumor suppressors by negatively regulating the activation of STATs." (PMID 30987235, 2019). "In myeloid cell-specific SOCS3-conditional knockout mice, SOCS3−/− macrophages simultaneously suppressed inflammation and tumor metastasis; therefore, SOCS3 is still considered a therapeutic target for cancer immunotherapy in DCs." (PMID 30658461, 2019).
tumor (continued). "Aberrantly strong JAK/STAT signaling in tumor cells can stimulate tumor growth, and SOCS3-mediated inhibition can reduce this effect and slow the growth of tumors." (PMID 31748225, 2019). "In this way, SOCS1 and SOCS3 also act as fail-safe tumor suppressors in response to aberrant JAK/STAT signaling." (PMID 31557897, 2019). "Although T3b-SOCS3 cKO mice underwent SOCS3 deletion in both small and large intestines as well as in stomach, the tumor was restricted in the stomach." (PMID 31141984, 2019). "After tumor formation in nude mice, the expression of miR-221-3p, SOCS3 and proteins in JAK/STAT signaling pathway were detected by RT-qPCR and western blot." (PMID 31222560, 2019). "More and more study indicated that Socs3 is a tumor suppressor except for the suppressor of cytokine signaling." (PMID 29545936, 2018). "The quite the opposite effect of rIL-6 and tumor microenvironment with high IL-6 on both e-MDSCs accumulation and SOCS3 expression also suggested that IL-6-related tumor-derived factors, but not IL-6 directly influenced SOCS3 suppression." (PMID 30083161, 2018). "Tumor-derived IL-6 impaired the differentiation of myeloid cells and promoted the accumulation of e-MDSCs by inhibiting SOCS3 expression and persistently activating the JAK/STAT signaling pathway." (PMID 30083161, 2018). "But surprisingly, we found that e-MDSCs exposed in high IL-6 expressing tumor microenvironment presented SOCS3 suppression and sustained activation of JAK/STAT, while IL-6 short stimulation caused temporary SOCS3 regulation and JAK/STAT activation." (PMID 30083161, 2018). "Socs3 plays its role both in expression of acute phase response and hepatocyte proliferation in LR and involves in hepatocarcinogenesis as a tumor suppressor." (PMID 29545936, 2018). "But long-term IL-6 stimulation in local tumor microenvironment executed significant inhibitory effect on SOCS3 in myeloid cells and thus induced sustained activation of the JAK/STAT pathway." (PMID 30083161, 2018). "The genetic deletion of SOCS3, specifically in myeloid cells, significantly enhances tumor growth, which correlates with elevated levels of MDSCs in the tumor microenvironment." (PMID 28228755, 2017). "Substantial data demonstrate the link between SOCS3 regulation of inflammation and its suppressor activity on tumor initiation and development." (PMID 28404963, 2017). "Their findings clearly demonstrated the importance of SOCS3 in restricting MDSC-mediated immunosuppression activity in tumor." (PMID 28228755, 2017). "The hypermethylated tumor tissues had significantly decreased SOCS3 mRNA expression than non hypermethylated tumor tissues (P=0.0023)." (PMID 28179578, 2017). "SOCS1 methylation was identified in 105 (42.7%) of the tumor tissues and the number for SOCS3 methylation status are164 (66.7%)." (PMID 28404963, 2017). "Further work should be performed to verify the critical function of SOCS3 as a negative regulator of MDSCs development and function in tumor environment." (PMID 28228755, 2017). "Similar to PTEN, however, SOCS3 acts a tumor suppressor, an effect likely mediated via the JAK/STAT pathway." (PMID 28824380, 2017). "As the pivotal negative regulators of cytokine signaling both in tumor cells and immunocytes, the dysregulation of the expression and function of SOCS1 and SOCS3 proteins significantly promotes tumor growth, migration, and invasion." (PMID 28228755, 2017). "Nevertheless, considering the disparity in the expression patterns of SOCS1 and SOCS3 in tumor cells and immunocytes, contradicting therapeutic approaches have been proposed." (PMID 28228755, 2017). "When the respective phosphorylation sites were mutated in SOCS-1 or SOCS-3, BCR-ABL induced tumor formation was completely blocked in nude mice due to “activation” of SOCS-1 or SOCS-3." (PMID 28753604, 2017).
tumor (continued). "Suppressor of cytokine signaling 3 (SOCS3) is a tumour suppressor, limiting intestinal epithelial cell (IEC) proliferation in acute inflammation, and tumour growth, but little is known regarding its role in mucosal homeostasis." (PMID 28508554, 2017). "It has been demonstrated that knockdown of SOCS3 in macrophages is beneficial for inhibiting tumor metastases in mice." (PMID 29326716, 2017). "The tumor promoting effect of IL-6 is mainly exerted by activation of the oncogenic transcription factors STAT3 and NF-κB, whereas loss of SOCS3 is important for further CAC progression." (PMID 28881611, 2017). "Suppressor of cytokine signaling 3 can act either as an oncogene or a tumor suppressor, depending on cellular context." (PMID 28228755, 2017). "Suppressor of cytokine signaling 3 regulates numerous tumors through inhibition of various signaling pathways and functioning as a tumor suppressor gene." (PMID 28228755, 2017). "SOCS1 and SOCS3 are important regulators of tumor-infiltrated T cell, dendritic cells (DCs), myeloid-derived suppressor cells (MDSCs), and macrophages." (PMID 28228755, 2017). "The interaction of SOCS3 with M2-PK reduces the ATP production and weakens the curative effect of antitumor immune therapy, which indicates that SOCS3 manipulates the activation and function of DCs in the tumor microenvironment." (PMID 28228755, 2017). "We found that presence of SOCS3 methylation is significantly associated with the major clinical features of HCC patients, including tumor stage, lymph node and vascular invasion." (PMID 28404963, 2017). "Aimed at rescuing SOCS3 activity in these tumor contexts, a SOCS3-derived peptide, named KIR-ESS, was synthesized, and its ability in suppressing IL-22-induced responses was evaluated in healthy and transformed keratinocytes." (PMID 28445952, 2017). "The role of SOCS3 in cancer is still controversial, because SOCS3 has been reported as a tumor-suppressor or tumor-promoting molecule, in different tumors." (PMID 29020964, 2017). "We observed that the SOCS3 promoter region was methylated in 26/37 (70.3%) liver tumor tissues while only in 11/37 (29.7%) adjacent non-tumor tissues showed methylation patterns (OR=5.4, 95%CI=1.9-17.1, P=0.0011)." (PMID 28179578, 2017). "Our results showed that miR-455-5p promotes tumor growth and metastasis through inhibiting SOCS3 in NSCLC." (PMID 29383133, 2017). "Suppressor of cytokine signaling 3 (SOCS3) acts as a tumour suppressor and regulator of inflammatory signaling pathways." (PMID 28508554, 2017). "Similar to SOCS1, the expression and function of SOCS3 vary significantly among different tumor types." (PMID 28228755, 2017). "It has been reported that SOCS3 has the potential of anti-tumor in many human cancers such as breast cancer, ovarian cancer and HCC." (PMID 28969053, 2017). "SOCS3, as a tumor suppressor, has been reported to be silenced in several human cancers including HCC." (PMID 28969053, 2017). "In this study, we found that SOCS3 (a tumor suppressor molecule) was significantly downregulated in HCC." (PMID 28969053, 2017). "Subsequently, we analyzed methylation status in the SOCS3 promoter in 37 pairs of tissue samples (tumor and adjacent non-tumor tissues)." (PMID 28179578, 2017). "SOCS3−/− mice also exhibited decreased tumor formation (71%; 10/14) when compared to SOCS3fl/fl mice (100%; 15/15)." (PMID 26967393, 2016). "The gene expression bead array results indicated that miR-124-3p, a tumor suppressor, was significantly affected by SOCS3." (PMID 27516205, 2016). "Consistently, the tumor suppressing effects of SOCS3 were partially neutralized by the miR-124-3p inhibitor." (PMID 27516205, 2016). "We found that SOCS3−/− tumor bearing mice have significantly increased CD8+ T-cell infiltration and significantly decreased Treg infiltration in the brains/tumors." (PMID 26967393, 2016).
tumor (continued). "Recently, reports have indicated that the LysMCre efficiency in microglia is less than 25%; thus, in our model, some expression of SOCS3 would be retained in microglia following the conditional deletion and theoretically still aide tumor growth." (PMID 26967393, 2016). "Overall, the anti-tumor effects leading to prolonged survival in the SOCS3−/− mice we observed can be attributed to GAMs, which have infiltrated from the periphery and are the major population of infiltrating cells." (PMID 26967393, 2016). "The up-regulation of FXR and SOCS3 was further validated by RT-PCR analysis on tumor tissue samples." (PMID 26899873, 2016). "We found that SOCS3-deficient bone marrow-derived macrophages (BMDM) display enhanced and prolonged expression of pro-inflammatory M1 cytokines when exposed to GL261 tumor cell conditioned medium in vitro." (PMID 26967393, 2016). "Our findings indicated that SOCS3 hypermethylation has already happened in non-tumor tissues and increased in both frequency and intensity in tumor tissues." (PMID 26393582, 2015). "We suggest that BSN inhibits STAT3 signaling through modulation of PIAS-3 and SOCS-3, thereby attenuating tumor growth and increasing sensitivity to paclitaxel." (PMID 25788267, 2015). "The SOCS3 signal was positive in only 27.27% (6 cases) of the tumor tissues, while it was positive in all corresponding peritumoral biliary tissues." (PMID 26485275, 2015). "In liver, lung, and squamous head and neck cancer, as well as a number of hematological malignancies, SOCS3 functions as a classical tumor suppressor." (PMID 26485275, 2015). "In HCC tumor tissues, SOCS3 showed an increased methylation frequency and intensity compared with that in the adjacent non-tumor tissues." (PMID 26393582, 2015). "In a further in vivo experiment, the tumor formed by cells co-transfected with SOCS3 and HIF-1α exhibited a higher growth rate and level of angiogenesis compared with that of cells transfected with Ad5-SOCS3 only." (PMID 25695729, 2015). "The protein expression level of SOCS3 in CCA tumor tissues was conspicuously lower than that in the corresponding peritumoral biliary tissues (7.56-fold on average, P < 0.0001), and it was also lower than that in normal biliary duct tissues." (PMID 26485275, 2015). "SOCS3 is involved in the development and progression of several malignancies, and there are indications that SOCS3 has different functions depending on the tumor origin." (PMID 25849377, 2015). "Then we examined the influence of FXR agonist on tumor growth and SOCS3 expression in HCC tumor xenograft model." (PMID 26416445, 2015). "The results indicated that SOCS3 expression was significantly lower in CCA tumor tissues than in corresponding peritumoral biliary tissues and normal bile duct tissues." (PMID 26485275, 2015). "Our findings suggested that SOCS3 hypermethylation has already happened in non-tumor tissues, while its frequency and intensity were increased in tumors." (PMID 26393582, 2015). "Compared with the tumor formed by cells transfected with the empty vector Ad5, tumors overexpressing SOCS3 exhibited a lower growth rate and lower rate of angiogenesis." (PMID 25695729, 2015). "Restoring the genetic function of the SOCS3 gene by demethylation or SOCS3 gene transfection was shown to suppress tumor cell growth by attenuating activation of signal transducer and activator of transcription 3 (STAT3) in several human cancer cell lines." (PMID 25695729, 2015). "Linear regression analysis further revealed that the A20 level was inversely correlated with SOCS3 expression in CCA tumor tissues and normal biliary duct tissues (R2 = 0.8232, P < 0.0001)." (PMID 26485275, 2015). "SOCS3 is a tumor suppressor in the intestine, as IEC-targeted deletion of SOCS3 promotes tumor burden in the colon, with methylated silencing of SOCS3 shared in multiple tumor types." (PMID 25377316, 2015).
tumor (continued). "Although the downregulation of SOCS3 has been regarded as crucial in tumor proliferation and migration, few studies have assessed the prognostic role of SOCS3 in human CCA." (PMID 26485275, 2015). "Using western blot analysis, the SOCS3 signal was positive in only 27.27% (6 cases) of the freshly frozen CCA tumor tissues, while it was positive in all (22 cases) corresponding peritumoral biliary tissues." (PMID 26485275, 2015). "In human tumors, SOCS3 expression identifies macrophages with enhanced tumor killing, whereas SOCS1 expressing macrophages (M2) favor tumor survival." (PMID 25120543, 2014). "In line with this, macrophage-specific SOCS3 knockout animals are resistant to tumor transplantation due to reduced secretion of tumor-promoting TNF-α and IL-6, together with elevated MCP2/CCL8 that is anti-tumorigenic." (PMID 25120543, 2014). "These SOCS3-deficient macrophages produce less IL-6 and TNF-α upon stimulation with tumor lysates due to aberrant STAT3 activity, again showing a positive link of SOCS and macrophage polarization." (PMID 25120543, 2014). "Forced activation of Notch signaling enhances both M1 polarization and anti-tumor activity via SOCS3 induction." (PMID 25120543, 2014). "It is worth noting that the authors found a low level of suppressor of cytokine signaling-3 (SOCS3) in this tumor model, which normally serves to inhibit STAT3 and self-regulate the duration of activation." (PMID 24877061, 2014). "Recently, some studies have reported that SOCS3 functions as a tumor suppressor in multiple tumor types, including GBM." (PMID 24633048, 2014). "Our results also indicate that the reduced expression and functional activity of SOCS3 is of relevance for HNSCC cell proliferation, migration and invasion suggesting SOCS3 has a role in HNSCC tumor progression." (PMID 23028842, 2012). "Our data indicate that the loss of SOCS3 expression in HNSCC is an early event that is maintained and even discretely accentuated with tumor progression, implicating this gene not only in tumorigenesis but also in tumor progression and invasion." (PMID 23028842, 2012). "Analysis of tissue microarrays indicated that loss of SOCS3 is an early event in HNSCC and was correlated with tumor size and histological grade of dysplasia, but a considerable proportion of cases presented detectable expression of SOCS3." (PMID 23028842, 2012). "This notion is further supported by the finding that restoring SOCS3 expression in tumor cell lines results in growth suppression and induction of apoptosis." (PMID 23028842, 2012). "The DFS curve for women with tumours which were classified as having 'high levels' of SOCS3 transcript was found to differ significantly from that of their 'low level' counterparts, showing a significant benefit in predicting better DFS (p = 0.024)." (PMID 20433750, 2010). "Specific silencing of SOCS3 expression in intestinal epithelial cells (IEC) increased tumor load in the azoxymethane/dextran sodium sulfate (AOM/DSS) mouse model of inflammation-associated CRC." (PMID 20500855, 2010). "SOCS3 in proliferative phase epithelium was significantly higher compared to epithelium in post-menopausal controls and all Tumour Grades." (PMID 20553623, 2010). "In tumours with high SOCS3 and 7 mRNA expression levels, epithelial tumour cells showed cytoplasmic staining for the respective SOCS proteins." (PMID 20433750, 2010). "IL11 increased pSTAT3/STAT3 in all tumour cell lines, while SOCS3 abundance was increased only in one tumour cell line." (PMID 20553623, 2010). "pSTAT3 was found in both the tumour epithelial and stromal compartments but was maximal in the tumour epithelial cells, while SOCS3 was predominantly found in the tumour epithelial cells." (PMID 20553623, 2010). "Our laboratory has also demonstrated that exogenously administered IFN-α induced profound in vivo anti-tumor activity that was immune-mediated (via CD8+ T cells) in SOCS1 and SOCS3 deficient mice." (PMID 20398276, 2010).